TUBB8P7 (tubulin beta 8 class VIII pseudogene 7)
Gene: Transcribed unprocessed pseudogene on chromosome 16 (90,094,023 to 90,096,188, forward strand). Ensembl gene ENSG00000261812.
Diseases named in the same sentence as TUBB8P7 in open-access papers:
TUBB8P7 is named in the same sentence as 1 disease in open-access papers, as found by Europe PMC text mining. Sharing a sentence is not in itself a finding about the gene and the disease.
TUBB8P7 shares sentences with these, for which no sentence is quoted: breast carcinoma (1 paper).